MAOA (monoamine oxidase A)
Diseases named in the same sentence as MAOA in open-access papers (continued):
Sharing a sentence is not in itself a finding about the gene and the disease.
heroin addiction (2 papers, 2017 to 2022). "In conclusion, we found that the MAOA rs1137070 was significantly associated with the susceptibility to heroin addiction and changes in GM." (PMID 28345608, 2017). "The low-activity C allele of MAOA rs1137070 was associated an increased susceptibility to heroin addiction." (PMID 28345608, 2017). "The present study investigated the association between the MAOA rs1137070 polymorphism and heroin addiction and related brain morphological and neurocognitive abnormalities." (PMID 28345608, 2017). "MAOA rs1137070 was associated with both the risk of onset of heroin addiction and also its progression." (PMID 28345608, 2017). "The results showed that the MAOA rs1137070 had an allelic association with heroin addiction." (PMID 28345608, 2017). "We examined the association between MAOA rs1137070 and heroin addiction." (PMID 28345608, 2017). "The function of the ACC-centered network may be critical for mediating the genetic effect of MAOA rs1137070 on heroin addiction." (PMID 28345608, 2017).
hypogonadism (2 papers, 2020 to 2021). A disorder characterized by decreased function of the gonads. "Thus, the aim of this work was to study the distribution of MAOA and MAOB polymorphisms in a group of nondiabetic obese patients with and without hypogonadism to discern the possible relationship between this genetic factor with the blood pressure in hypogonadism." (PMID 31743621, 2020).
Pancreatic Carcinoma (2 papers, 2024). "High levels of IDO, TPH1, HTR2B, AhR, and Kyn predict a poor prognosis in pancreatic cancer, whereas MAOA expression is negatively correlated with TNM stage and tumor size in pancreatic cancer, predicting a favorable prognosis." (PMID 38462620, 2024). "In pancreatic cancer tissues, levels of 3-IAA, 5-HT, KYNU, IDO, and TPH1 are significantly elevated, while levels of MAOA, 3-hydroxyanthranilic acid 3,4-dioxygenase (HAAO), and quinolinic acid phosphoribosyltransferase (QPRT) are markedly downregulated." (PMID 38462620, 2024).
renal cell carcinoma (2 papers, 2020 to 2021). "In addition, increased expression of MAOA has been identified in high-grade carcinomas of renal cell cancer." (PMID 34209963, 2021).
Sepsis (2 papers, 2023). Sepsis is defined as life-threatening organ dysfunction caused by a dysregulated host response to infection. "The septic rat model was established to verify the effect of phenylalanine metabolism-related gene MAOA on survival and mean arterial pressure after sepsis." (PMID 37946144, 2023). "Additionally, an analysis of transcriptome data from sepsis patients in the GEO database revealed a significant up-regulation of the phenylalanine-metabolism-related gene MAOA in the sepsis group." (PMID 37946144, 2023). "Recent studies have shown that MAOA is correlated with sepsis-induced cardiac dysfunction." (PMID 38011291, 2023). "Additionally, analysis of transcriptome data from sepsis patients in the GEO database revealed a significant up-regulation of the phenylalanine metabolism-related gene MAOA in sepsis." (PMID 37946144, 2023). "Moreover, it specifically examined the alterations in phenylalanine metabolism following sepsis and subsequently analyzed the regulatory mechanism of MAOA." (PMID 37946144, 2023). "To demonstrate the impact of MAOA in sepsis, we employed a sepsis model in rats using CLP (cecal ligation and puncture) and observed the effect of MAOA inhibition through its antagonist, RS-8359." (PMID 37946144, 2023). "However, sepsis cases with increased levels of mRNA of DHCR7, GABARAPL2, MAOA, MPO, PDZD8, and TFRC had worse overall survival." (PMID 38011291, 2023).
stress-related disorder (2 papers, 2023). Stress-related disorders are mental health disorders that are a result of an atypical response to both short and long-term anxiety due to physical, mental, or emotional stress. "In the review of stress-related disorders and MAOA methylation, decreased methylation levels were detected in patients compared to controls or in patients before treatment compared to the same patients after treatment." (PMID 37185702, 2023).
adrenal neoplasm (1 paper, 2023). "In a univariate analysis that examined the impact of amine oxidase family expression in adrenal neoplasm on prognosis, a low MAOA (S) expression in ACN was associated with shorter OS (p = 0.008)." (PMID 37509535, 2023).
behavioural addiction (1 paper, 2021). "Although, our understanding of mRNA expression of PIU-related genes is inadequate, the present findings provide promising evidence to support that the increased MAOA mRNA level may be a cause of behavioural addiction." (PMID 34335325, 2021). "Abnormalities of the MAOA gene have been found to be closely related to various neurological and mental disorders, such as behavioural addiction." (PMID 34335325, 2021).
bladder tumor (1 paper, 2023). "In a rat bladder tumor cell line, reduced ROS production by MAOA inhibition reduced expression of proteins involved in glucose transport, such as GLUT1." (PMID 37371714, 2023).
brain injury (1 paper, 2019). Acute and chronic (see also brain INJURIES, CHRONIC) injuries to the brain, including the cerebral hemispheres, CEREBELLUM, and brain STEM. "The mean prison sentence assigned by law students differed only slightly, and the group differences were not significant (“Absent Biomechanism” group: 9.15 years, “Brain Injury” group: 10.06 years, “MAOA Gene”: 10.54 years)." (PMID 31681122, 2019).
carotid atherosclerosis (1 paper, 2012). A thickening and loss of elasticity of the walls of carotid arteries that occur with formation of atherosclerotic plaques. "In summary, in a matched monozygotic twin sample, we found that the association between MAOA promoter methylation and carotid atherosclerosis is largely explained by genetic predisposition and/or family environment shared by the twins." (PMID 23116433, 2012). "The purpose of this study is to investigate the association between DNA methylation variation in the MAOA promoter region and carotid atherosclerosis, assessed by common carotid intima-media thickness (IMT), using a monozygotic co-twin control design." (PMID 23116433, 2012).
colitis (1 paper, 2026). Inflammation of the colon. "AS-IV ameliorated colitis by downregulating IDO1 expression, while upregulating the expression of tryptophan hydroxylase 1 (TPH1), DDC, monoamine oxidase A (MAO-A), and the aryl hydrocarbon receptor (AhR), as well as inhibiting NF-κB p65 phosphorylation." (PMID 42195848, 2026).
coronary artery atherosclerosis (1 paper, 2021). "Comparing the targets of the herbal strategies and three existing drugs (atenolol, pravastatin and propranolol) and the symbols of coronary artery atherosclerosis, we discovered that MAOA, HTR1A, and ABCG2 are overlapping in the three groups." (PMID 34012683, 2021). "Notably, MAOA is common target in four herbal strategies and propranolol, with HTR1A in strategy IV and propranolol, and ABCG2 in four herbal strategies and pravastatin, and in coronary artery atherosclerosis." (PMID 34012683, 2021).
coronary heart disease (1 paper, 2021). "MAOA inhibitor appreciably attenuates constant impairment of endothelial-dependent relaxation in patients with coronary heart disease aside from in human mammary arteries." (PMID 34012683, 2021).
drug dependence (1 paper, 2018). "These rich data allowed us to determine that the observed association between SA and MAOA first exon methylation levels were robust to adjustment for lifetime and current use of psychoactive medications, lifetime and current diagnoses of alcohol and drug dependence, and current alcohol and drug use." (PMID 29600412, 2018). "SA, not PA, was associated with hypermethylation of the MAOA first exon relative to no-abuse, and the association was robust to adjustment for psychoactive medication, alcohol and drug dependence, and current substance use." (PMID 29600412, 2018).
hemophilia (1 paper, 2018). Hemophilia is a genetic disorder characterized by spontaneous hemorrhage or prolonged bleeding due to factor VIII or IX deficiency. "In case of disrupted promotion of gene (e.g.: MAOA) carried by X, this epigenetic regulation—known as ‘chromosome silencing’—allows the safe-X cells to compensate for the other ones, like in hemophilia “healthy carriers”." (PMID 30558545, 2018).
hyperlipidemia (1 paper, 2021). "Similarly, ESR1(ERα), MAOA, MGAM, PTK2, MMP1, GNB5, PIK3R3, and other targets had higher degree values, suggesting that these genes might be the core targets of PCE intervention in hyperlipidemia." (PMID 34925692, 2021).
inflammatory bowel disease (1 paper, 2025). A spectrum of small and large bowel inflammatory diseases of unknown etiology. "This study underscores the pivotal role of serotonin metabolism in pediatric inflammatory bowel disease pathogenesis, with elevated TPH1 expression in the inflamed transverse colon and reduced MAOA expression in regions like the ileum and descending colon driving an inflammatory imbalance." (PMID 41465348, 2025).
influenza (1 paper, 2024). An acute viral infection of the respiratory tract, occurring in isolated cases, in epidemics, or in pandemics; it is caused by serologically different strains of viruses (influenzaviruses) designated A, B, and C, has a 3-day incubation period, and usually lasts for 3 to 10 days. "The ten common DEGs (PCOLCE2, HLA_DPA1, LOC653061, TDRD9, MPO, HLA_DQA1, MAOA, S100P, RAP1GAP, and CA1) that were obtained by overlapping genes from computing the three algorithms [LASSO regression, SVM-RFE algorithms, and RF are candidate key genes for severe influenza." (PMID 38454348, 2024). "In contrast, PCOLCE2, TDRD9, MPO, MAOA, RAP1GAP, and S100P expression was higher in the severe influenza group compared to the non-severe influenza group in the training cohort, similar to the findings in the validation cohort." (PMID 38454348, 2024).
lipoma (1 paper, 2021). A benign, usually painless, well-circumscribed lipomatous tumor composed of adipose tissue. "Similarly, PDE3A, a major cAMP degradation enzyme, is upregulated in lipoma acting synergistically together with the increase MAOA reducing the lipolytic tone in lipoma." (PMID 33235355, 2021).
malaria (1 paper, 2024). Malaria is a serious and sometimes fatal disease caused by a parasite that commonly infects a certain type of mosquito which feeds on humans. "This pioneering study explores the influence of monoamine oxidase-A (MAO-A) on primaquine metabolism and its impact on malaria relapses." (PMID 38870082, 2024).
metastasis (1 paper, 2025). The spread or migration of cancer cells from one part of the body (where they first appeared) to another. "For instance, elevated levels of MAOA were observed in non-small cell lung cancer (NSCLC) compared to non-tumor tissues, with MAOA expression showing positive correlations with clinical stages and lymph node metastasis." (PMID 41338163, 2025).
neuroendocrine tumors (1 paper, 2017). "Our results here show MAOA as a new decision-maker for activating autophagy and MAOA inhibitors may be useful as a potential therapy for neuroendocrine tumors." (PMID 28402333, 2017).
non-Hodgkin lymphoma (1 paper, 2017). Distinct from Hodgkin lymphoma both morphologically and biologically, non-Hodgkin lymphoma (NHL) is characterized by the absence of Reed-Sternberg cells, can occur at any age, and usually presents as a localized or generalized lymphadenopathy associated with fever and weight loss. "No MAOA was found in non-neoplastic lymphoid tissues, nodular lymphocyte-predominant Hodgkin lymphoma (NLPHL, 0/8), or any other non-Hodgkin lymphomas studied (NHL, 0/123)." (PMID 29057015, 2017).
ocular hypertension (1 paper, 2022). Abnormally high intraocular pressure. "The increase in the activity of acetylcholinesterase (AChE), butyrylcholinesterase (BuChE) and monoamine oxidase-A (MAO-A) is also responsible for the occurrence of HBP and an increased risk of developing ocular hypertension and related complications." (PMID 36362630, 2022).
osteoarthritis (1 paper, 2024). A noninflammatory degenerative joint disease occurring chiefly in older persons, characterized by degeneration of the articular cartilage, hypertrophy of bone at the margins and changes in the synovial membrane. "Overall, we postulate that curcumin might have therapeutic potential in the management of osteoarthritis by targeting CBS, PSAT1, MAOA, and other crucial proteins." (PMID 37938371, 2024). "For instance, curcumin may exhibit therapeutic effects on osteoarthritis by modulating the CBS, CTH, PSAT1, MAOA, and AOC2 proteins involved in the metabolism of glycine, serine, and threonine." (PMID 37938371, 2024).
perinatal depression (1 paper, 2015). "Finally, two further genes implicated in monoaminergic pathways, namely catechol-O-methyltransferase (COMT) and monoamine oxidase A (MAO-A) have also been associated with perinatal depression during stress exposure." (PMID 27617302, 2015).
rheumatoid arthritis (1 paper, 2020). A chronic, systemic autoimmune disorder characterized by inflammation in the synovial membranes and articular surfaces. "The 184 intersection genes of the MAOA negatively related CEGs and upregulated DEGs were significantly related to lymphocytic choriomeningitis and were primarily enriched in the KEGG pathway of rheumatoid arthritis." (PMID 32931665, 2020).
Right ventricular hypertrophy (1 paper, 2011). In this case the right ventricle is more muscular than normal, causing a characteristic boot-shaped (coeur-en-sabot) appearance as seen on anterior- posterior chest x-rays. "Our findings indicate an association between right ventricular hypertrophy and the expression of MAOA." (PMID 21246034, 2011). "Reactive oxygen species (ROS), a product from oxidation of 5-HT catalyzed by MAOA, is related to right ventricular hypertrophy and ROS has been found to be located to the mitochondria." (PMID 21246034, 2011).
stereotypies (1 paper, 2018). "Indeed, stereotypies have been reduced by a 5-HT reuptake inhibitor (SSRI) in MAOA-KO mice, which questions the GP model." (PMID 30558545, 2018).
tuberculosis (1 paper, 2020). A chronic, recurrent infection caused by the bacterium Mycobacterium tuberculosis. "Isoniazid (INH) is an irreversible inhibitor of Monoamine oxidase A (MAOA) that is widely regarded as a major anti-tuberculosis drug." (PMID 32391058, 2020).
Venous thrombosis (1 paper, 2026). Formation of a blood clot (thrombus) inside a vein, causing the obstruction of blood flow. "MAOA may modulate the concentrations of inflammatory mediators and thereby influence the development of venous thrombosis." (PMID 41602836, 2026).
X-linked disease (1 paper, 2020). X-linked form of disease. "In conclusion, our results may demonstrate the mechanism of Bap31 on MAOA-associated X-linked diseases." (PMID 32426368, 2020).
cancer (83 papers, 2002 to 2026). A tumor composed of atypical neoplastic, often pleomorphic cells that invade other tissues. "Single-cell analysis revealed AEBP1 was mainly expressed in cancer-associated fibroblasts, while MAOA was enriched in cancer cells." (PMID 41836296, 2026). "Research advances have implicated abnormal MAOA activity in aggressive cancers, including prostate, lung, brain, colon, melanoma, Hodgkin lymphoma, and breast cancer." (PMID 39904854, 2025). "Glucocorticoid-treated, ARSI-resistant epithelial cells and cancer-associated fibroblasts shared a four-gene glucocorticoid-receptor (GR) core in which monoamine-oxidase-A (MAO-A) was the dominant direct GR target." (PMID 40806607, 2025). "Current antidepressants such as MAOA inhibitors and SSRIs can effectively prevent AN use and avoid cancer risk." (PMID 37190117, 2023). "Clinical data correlation studies associate high intratumoral MAOA expression with poor patient survival in a broad range of cancers." (PMID 34112755, 2021). "Monoamine oxidase A (MAO-A) is an outer mitochondrial membrane-bound enzyme best known for its function in the brain, but also linked to cancer progression." (PMID 34112755, 2021). "Monoamine Oxidase A (MAO A) oxidizes monoamine neurotransmitters resulting in reactive oxygen species which cause cancer." (PMID 26871599, 2016). "Finally, clinical data correlation studies associated intratumoral MAOA expression with T cell dysfunction and decreased patient survival in a broad range of cancers." (PMID 39405979, 2024). "Interestingly, the MAOA/HIF1α signaling pathway was later found to be responsible for EMT induced by cancer-associated fibroblasts in PC as well." (PMID 36860320, 2023). "Deficiency of MAOA renders cancer cells resistant to ferroptosis upon 5‐HT treatment." (PMID 36627132, 2023). "In addition, MAOA expression is elevated in the prostate stromal cells associated with cancer relative to normal counterparts, which reprograms the stroma to a more reactive and pro-tumorigenic state through increased oxidative stress to promote PC development, growth and stemness." (PMID 36860320, 2023). "Moreover, increased expression of MAOB mRNA was significantly associated with COMT mRNA in the same cancer tissues (ρ = 0.738; p < 0.001), and increased expression of MAOA mRNA was significantly associated with COMT mRNA in the same cancer tissues (ρ = 0.557; p < 0.001)." (PMID 34209963, 2021). "Treatment with the DNA methyltransferase (DNMT) inhibitor, 5-aza-2′-deoxycytidine (5-Aza), was shown to upregulate MAOA in both cancer types." (PMID 41338163, 2025). "When comparing the results of MAOA expression in different cancers, they are inconsistent and differ per malignancy." (PMID 41465541, 2025). "Specifically, NMI was shown to bind MAOA and the blood carrier protein, albumin, providing insights to image and treat cancer." (PMID 39904854, 2025). "Although MAOA is the preferred target, NMI must first pass through the blood via albumin, enter the cancer cell, and bind MAOA on the outer mitochondrial surface." (PMID 39904854, 2025). "Cancer-associated fibroblasts (CAFs) are the most abundant and important type of stromal cells in the PCa TME, and MAOA expression in CAFs increases in parallel with cancer progression." (PMID 38349393, 2024). "While much remains to be explored regarding MAOA, existing evidence suggests its multifaceted role in cancer." (PMID 39010072, 2024). "The MAOA neurotransmitter catabolic enzyme was previously reported to be upregulated in PCa and to exert an oncogenic role in promoting tumorigenesis and cancer metastasis." (PMID 38520217, 2024). "First, further investigations into the mechanisms of MAOA in cancer development and its interactions with other biomarkers and signaling pathways are warranted." (PMID 39010072, 2024). "The findings of one study identified MAOA as a critical regulator of TAMs and supported repurposing MAOAIs for reprogramming TAMs to improve cancer immunotherapy." (PMID 38349393, 2024).